RNU6-832P (RNA, U6 small nuclear 832, pseudogene)
Gene: Small nuclear RNA gene on chromosome 7 (69,125,270 to 69,125,376, forward strand). Ensembl gene ENSG00000200189.
Homologues: Orthologues: chimpanzee U6 (99% identical), macaque U6 (88% identical), mouse Gm24491 (84% identical), rabbit U6 (82% identical), rabbit U6 (78% identical). Paralogues in human: RNU6-11P (90% identical), RNU6-37P (90% identical), RNU6-41P (90% identical), RNU6-1175P (89% identical), RNU6-25P (89% identical), RNU6-29P (89% identical), RNU6-1 (88% identical), RNU6-1145P (88% identical), RNU6-116P (88% identical), RNU6-12P (88% identical), RNU6-13P (88% identical), RNU6-15P (88% identical), and 1287 more.